DCP1B (decapping mRNA 1B)
Description:
May play a role in the degradation of mRNAs, both in normal mRNA turnover and in nonsense-mediated mRNA decay. May remove the 7-methyl guanine cap structure from mRNA molecules, yielding a 5'-phosphorylated mRNA fragment and 7m-GDP (By similarity).
Synonyms: FLJ31638; DCP1
Tractability: PROTAC: ubiquitination databases record sites on it; its protein half-life has been measured.
Gene: Protein-coding gene on chromosome 12 (1,946,052 to 2,004,535, reverse strand). Ensembl gene ENSG00000151065.
Subcellular location: Cytoplasm; Nucleus
Subcellular location (Human Protein Atlas): Cytosol; Vesicles
Pathways (Reactome):
Metabolism of RNA: mRNA decay by 5' to 3' exoribonuclease
Gene Ontology:
Molecular function: protein binding; 5'-(N(7)-methylguanosine 5'-triphospho)-[mRNA] hydrolase activity; mRNA binding; enzyme activator activity
Biological process: deadenylation-dependent decapping of nuclear-transcribed mRNA; nuclear-transcribed mRNA catabolic process, deadenylation-dependent decay
Cellular component: cytoplasm; cytosol; membrane; nucleus; P-body; RNA decapping complex
Genetic constraint (gnomAD): Loss-of-function variants: 44 observed, 59.97 expected, observed/expected ratio (o/e) 0.73, 90% interval 0.57 to 0.94. The upper end of that interval is the gene's LOEUF score, 0.94, which puts it in group 4 of 6, group 1 being the genes least tolerant of losing a copy. Missense variants: 715 observed, 781.43 expected, observed/expected ratio (o/e) 0.91, 90% interval 0.86 to 0.97. Synonymous variants: 266 observed, 292.63 expected, observed/expected ratio (o/e) 0.91, 90% interval 0.82 to 1.01.
Homologues: Orthologues: chimpanzee DCP1B (99% identical), macaque DCP1B (95% identical), dog DCP1B (84% identical), guinea pig DCP1B (73% identical), rabbit DCP1B (71% identical), pig DCP1B (68% identical), rat Dcp1b (64% identical), mouse Dcp1b (64% identical), tropical clawed frog dcp1b (54% identical), zebrafish dcp1b (40% identical), Drosophila melanogaster DCP1 (19% identical), Caenorhabditis elegans dcap-1 (13% identical). Paralogues in human: DCP1A (29% identical).
Diseases named in the same sentence as DCP1B in open-access papers:
DCP1B is named in the same sentence as 15 diseases in open-access papers, as found by Europe PMC text mining. Sharing a sentence is not in itself a finding about the gene and the disease. The quoted sentences say what the papers report.
Obesity (3 papers, 2020 to 2023). Accumulation of substantial excess body fat. "The DCP1B gene, expressed in the brain, is associated with waist-to-hip ratio, BMI, and obesity-related traits, all risk factors of T2DM." (PMID 37033211, 2023). "Nevertheless, the rs2470397 minor C allele helps define haplotypes 3 and 6 that evidence an association between the rs11062091 minor A allele, low levels of DCP1B splicing, and an increased incidence of obesity." (PMID 37164635, 2023). "Located within the same 12p13.33 region, the genes DCP1B, TSPAN9, and FKBP4 also overlapped between hypomania and schizophrenia, and have previously been associated with a range of physical health phenotypes including obesity and waist–hip ratio." (PMID 32152294, 2020).
diabetic retinopathy (1 paper, 2023). "When investigating sub-phenotypes of T2DM, diabetic retinopathy has been identified to be associated with ACVRIC (rs4664229), ZFHX4 (rs61729527), WNT9B (rs4968281), SHANK3 (rs9616915), ZSCAN5A (rs7252603), and DCP1B (rs715146, rs1044950, rs113147414) gene." (PMID 37033211, 2023).
lung squamous cell carcinoma (1 paper, 2025). "Subgroup analysis showed that patients with higher expression of DCP1B had a better prognosis in both LUAD and lung squamous cell carcinoma (LUSC) cohorts." (PMID 40200093, 2025).
cancer (3 papers, 2019 to 2025). A tumor composed of atypical neoplastic, often pleomorphic cells that invade other tissues. "Together with the observation of dysregulation of DCP1b in numerous cancers, we speculate that DCP1b is also implicated in cancer pathogenesis, and further studies are required to fully understand the roles of DCP1a and DCP1b in cancer pathogenesis." (PMID 39485278, 2024). "While DCP1a and DCP1b have both been implicated in cancer, our observation of significant alterations in multiple cancer-related pathways in DCP1a-knockout cells suggests that DCP1a might be more prominently associated with cancer development." (PMID 39485278, 2024). "In contrast, DCP1b exhibited significant upregulation in certain cancer types while showing downregulation in others." (PMID 39485278, 2024). "This panel provides insights into the potential roles of DCP1a and DCP1b in different cancers, highlighting their differential expression patterns." (PMID 39485278, 2024). "Other hypermethylated age DMR genes from our data set classified two pathways relevant for growth and development (DCP1B, IGF1R, and FGF18) and cancer progression (TIAM1)—biological processes which has been also mentioned in the literature as epigenetic hallmarks of aging." (PMID 31281827, 2019).
tumor (2 papers, 2024 to 2025). "In FUSCC cohorts, DCP1B is decreased in tumor specimens, and the lower expression of DCP1B is associated with a worse prognosis of NSCLC patients." (PMID 40200093, 2025). "Our results showed that DCP1B deficiency significantly increased the xenograft tumor growth rate, resulting in larger tumor weight and size." (PMID 40200093, 2025). "In contrast, DCP1B exhibited distinct expression patterns across tumor types, with its prognostic implications varying depending on tumor subtypes." (PMID 40200093, 2025).
DCP1B also shares sentences with these, for which no sentence is quoted: adrenocortical carcinoma (1 paper); coronary heart disease (1); glioma (1); hypomania (1); non-small cell lung carcinoma (1); pancreatic adenocarcinoma (1); prostate adenocarcinoma (1); schizophrenia (1); uterine corpus endometrial carcinoma (1); uveal melanoma (1).